PRRT2 (proline rich transmembrane protein 2)
Description:
As a component of the outer core of AMPAR complex, may be involved in synaptic transmission in the central nervous system. In hippocampal neurons, in presynaptic terminals, plays an important role in the final steps of neurotransmitter release, possibly by regulating Ca(2+)-sensing. In the cerebellum, may inhibit SNARE complex formation and down-regulate short-term facilitation.
Synonyms: DSPB3; FLJ25513; DKFZp547J199; IFITMD1; FICCA; PKC; EKD1; BFIC2; BFIS2; DYT10; ICCA
Tractability: Antibody: UniProt places it where antibodies can reach, with high confidence; its Gene Ontology location is reachable by antibodies, with high confidence; UniProt predicts a signal peptide or a membrane-spanning region; the Human Protein Atlas places it where antibodies can reach. PROTAC: its protein half-life has been measured.
Gene: Protein-coding gene on chromosome 16 (29,811,382 to 29,815,892, forward strand). Ensembl gene ENSG00000167371.
Subcellular location: Cell membrane; Presynaptic cell membrane; Synapse; Cell projection, axon; Cytoplasmic vesicle, secretory vesicle, synaptic vesicle membrane; Postsynaptic density membrane; Cell projection, dendritic spine
Subcellular location (Human Protein Atlas): Plasma membrane
Gene Ontology:
Molecular function: protein binding; syntaxin-1 binding
Biological process: neuromuscular process controlling posture; negative regulation of short-term synaptic potentiation; negative regulation of SNARE complex assembly; synaptic vesicle fusion to presynaptic active zone membrane; regulation of calcium-dependent activation of synaptic vesicle fusion
Cellular component: plasma membrane; axon terminus; presynapse; presynaptic membrane; synapse; synaptic vesicle; vesicle; axon; dendritic spine; glutamatergic synapse; membrane; postsynaptic density membrane; synaptic vesicle membrane
Genetic constraint (gnomAD): Loss-of-function variants: 9 observed, 24.81 expected, observed/expected ratio (o/e) 0.36, 90% interval 0.22 to 0.63. The upper end of that interval is the gene's LOEUF score, 0.63, which puts it in group 2 of 6, group 1 being the genes least tolerant of losing a copy. Missense variants: 460 observed, 445.6 expected, observed/expected ratio (o/e) 1.03, 90% interval 0.96 to 1.12. Synonymous variants: 195 observed, 175.99 expected, observed/expected ratio (o/e) 1.11, 90% interval 0.99 to 1.25.
Gene-disease validity (ClinGen):
ClinGen rates the evidence that PRRT2 causes each of these diseases.
infantile convulsions and choreoathetosis (autosomal dominant): Definitive. A neurological condition characterized by the occurrence of seizures during the first year of life (Benign familial infantile epilepsy) and choreoathetotic dyskinetic attacks during childhood or adolescence.
Homologues: Orthologues: chimpanzee PRRT2 (99% identical), macaque PRRT2 (96% identical), guinea pig PRRT2 (84% identical), pig PRRT2 (84% identical), mouse Prrt2 (80% identical), dog PRRT2 (73% identical), rat Prrt2 (68% identical), zebrafish prrt2 (22% identical). Paralogues in human: TRARG1 (17% identical), PRRT1 (16% identical), PRRT1B (15% identical), TMEM233 (11% identical).
Diseases named in the same sentence as PRRT2 in open-access papers:
PRRT2 is named in the same sentence as 159 diseases in open-access papers, as found by Europe PMC text mining. Sharing a sentence is not in itself a finding about the gene and the disease. The quoted sentences say what the papers report.
epilepsy (65 papers, 2012 to 2026). A brain disorder characterized by episodes of abnormally increased neuronal discharge resulting in transient episodes of sensory or motor neurological dysfunction, or psychic dysfunction. "All children with epilepsy and either a pathogenic PRRT2 variant or 16p11.2 microdeletion encompassing the PRRT2 gene were included in this retrospective study." (PMID 40401013, 2025). "Overall, sodium channel blockers remain an effective treatment for epilepsy related to pathogenic PRRT2 variants." (PMID 40401013, 2025). "Collection of additional cases, however, is needed to better understand the epilepsy phenotypes associated with 16p11.2 microdeletions encompassing the PRRT2 gene and homozygous and compound heterozygous PRRT2 variants." (PMID 40401013, 2025). "The PRRT2 gene mutation has obvious phenotypic heterogeneity; heterozygous mutation of this gene often causes SeLFE, whereas homozygous mutation can cause epilepsy with intellectual disability." (PMID 40236662, 2025). "We describe additional 40 cases of epilepsy associated with pathogenic PRRT2 variants/16p11.2 microdeletions and supplement what is known about this condition." (PMID 40401013, 2025). "Collection of additional cases is needed, however, to better understand the spectrum of epilepsy phenotypes associated with 16p11.2 microdeletion encompassing the PRRT2 gene and homozygous and compound heterozygous PRRT2 variants." (PMID 40401013, 2025). "TBX6 has been associated with vertebral malformations and PRRT2 has been associated with epilepsy and paroxysmal dyskinesia." (PMID 39202413, 2024). "The hotspot variation c.649dupC (p.R217Pfs*8), identified in six cases, further supports its role as a diagnostic marker for BFIE, with prior studies reporting this variant in 50%–70% of PRRT2-related epilepsy cases globally." (PMID 39906551, 2024). "Of the 22 patients with mutations in the PRRT2 gene, nine patients had epilepsy and HM together, and five patients had only epilepsy." (PMID 38273253, 2024). "Here, the authors use proteomics to show dysregulation of synaptic and epilepsy-associated protein networks in the cortex of model mice, and demonstrate that correcting Prrt2 gene dosage rescues circuit hypersynchrony and behavioural phenotypes." (PMID 36808153, 2023). "The genetic analysis revealed that PRRT2, was a causative gene for an autosomal dominant form of epilepsy termed Benign Familial Infantile Seizures (MIM: 605751)." (PMID 36808153, 2023). "To date, most PRRT2 mutations have been labeled “benign” and lead to self-limited familial infantile epilepsy." (PMID 37228410, 2023). "Accordingly, patients bearing loss-of-function mutations in the PRRT2 gene or PRRT2 KO mice are affected by paroxysmal manifestations, whose pleiotropism ranges from paroxysmal kinesigenic dyskinesia to epilepsy and migraine." (PMID 36441479, 2023). "Bioinformatic prediction and protein:protein interaction analysis further identified PRRT2, a protein encoded within the 16p11.2 region, as a highly connected hub within the epilepsy subnetwork disrupted in 16p11.2dup/+ mice." (PMID 36808153, 2023). "In the # 8 “ptt2 mutation” cluster, we learned that PRRT2 is the most common single-gene epilepsy and common epilepsy type." (PMID 37505157, 2023). "CNVs at 16p11.2 involving the PRRT2 gene have been reported as benign but have previously been linked to epilepsy, and mutations of PRRT2 are associated with BIE." (PMID 38203422, 2023). "Our analysis showed that the co-expression network associated with SEZ6L2 (2.6 fold, p = 2.2 × 10−9) and PRRT2 (2.52 fold, p = 3.77 × 10−8) were the most highly enriched for proteins in the epilepsy subnetwork, making these priority candidates." (PMID 36808153, 2023). "With PRRT2-associated epilepsies, both a medication change and additional surveillance are recommended." (PMID 35627257, 2022).
epilepsy (continued). "Many details of PRRT2 function at the synapse, and the effects of mutations on neuronal excitability in the pathophysiology of epilepsy and dyskinesia, have emerged through the work of several groups over the last decade." (PMID 34101060, 2021). "In most cases, such phenotypes occur in combination with the classic syndromes associated with PRRT2 mutations (i.e., epilepsy and PxD), hence the importance of their recognition to aid the differential diagnosis, but can seldom occur in isolation." (PMID 33746883, 2021). "We screened a cohort of 492 children with epilepsy for mutations in the PRRT2 gene using whole exome sequencing (WES) and low‐coverage massively parallel CNV sequencing (CNV‐seq) (281 male and 211 female)." (PMID 32237035, 2020). "Point and copy number variant mutations in the PRRT2 gene have been identified in a variety of paroxysmal disorders and different types of epilepsy." (PMID 32237035, 2020). "So far an increased risk for respiratory disturbance or SUDEP cannot be associated with PRRT2-related epilepsy despite a single report on SUDEP in one patient, which would warrant further studies." (PMID 33126500, 2020). "While epilepsy in association with PRRT2 variants usually starts in infancy, movement disorders predominantly occur in adolescence and adulthood." (PMID 33126500, 2020). "PRRT2 mutations were found in only a few cases when 70 genes were genetically tested in 8565 patients with epilepsy and neurodevelopmental disorders." (PMID 31801583, 2019). "Heterozygous mutations in proline-rich transmembrane protein 2 (PRRT2) underlie a group of paroxysmal disorders, including epilepsy, kinesigenic dyskinesia, and migraine." (PMID 27052163, 2016). "Haploinsufficiency of CYFIP1 at 15q11.2, CHRNA7 at 15q13.3, NDE1 at 16p13.11 and PRRT2 at 16p11.2 has been implicated as risk-conferring mechanism for epilepsy and other neurodevelopmental phenotypes." (PMID 25950944, 2015). "The reported frequency of migraine among PRRT2 mutation carriers is significantly higher (27.1%) than in the overall population with epilepsy (8%-15%)." (PMID 24370076, 2013). "Three atypical epilepsy phenotypes were observed associated with heterozygous PRRT2 variants." (PMID 40401013, 2025). "16p11.2 microdeletion encompassing the PRRT2 gene was associated with a variable epilepsy/neurologic phenotype in our cohort ranging from SeLIE with well-controlled seizures to childhood-onset medically refractory GGE with intellectual disability and autistic features." (PMID 40401013, 2025). "Nevertheless, our additional case illustrates the spectrum of epilepsy that may occur with pathogenic PRRT2 variants, including later-onset FE." (PMID 40401013, 2025). "There are few cases (total = 4) in the literature that report individuals with both heterozygous PRRT2 variants and 16p11.2 microdeletion; all had epilepsy, and learning disabilities, intellectual disability, and autism spectrum disorder were seen in half of the cases." (PMID 40401013, 2025). "Consistent with this hypothesis, the 16p11.2 genes PRRT2 (MIM: 614386) and SEZ6L2 act as hubs in an epilepsy protein subnetwork dysregulated in a duplication mouse model and correcting the dosage of PRRT2 rescued seizure susceptibility." (PMID 39332410, 2024). "Activity levels below 50% may contribute to disease, and different levels of PRRT2 activity could be associated with epilepsy." (PMID 38203422, 2023). "Our work suggests that increased Prrt2 gene dosage causes an upregulation of PRRT2 at the membrane, which dysregulates epilepsy-associated protein networks, causes elevated circuit synchrony, increased glutamate release, which then impacts both seizure susceptibility and sociability." (PMID 36808153, 2023). "Physiological levels of PRRT2 seem to be necessary to maintain a normal level of network activity, so that an overexpression of PRRT2, occurring in the 16p11.2 duplication, is also associated with neuropsychiatric disorders including epilepsy." (PMID 36958475, 2023).
epilepsy (continued). "PRRT2 disease-causing variants are among the most common genetic causes of epilepsy." (PMID 35250833, 2022). "Delayed cortical migration is associated with many severe epileptic encephalopathies, and may explain why there is a developmental window for epilepsy in individuals with PRRT2 mutations." (PMID 34101060, 2021). "In this study, we analyzed the phenotypes and PRRT2‐related mutations in Chinese epilepsy children." (PMID 32237035, 2020). "In line with other forms of episodic ataxia, an overlap with headache disorders and epilepsy is present in PRRT2-associated neurological phenotypes and a common synaptic dysfunction might underlie these synaptopathies." (PMID 33126500, 2020). "Despite the lack of large-scale research evidence, existing reports indicate that common PRRT2 mutations are more likely to get remission through carbamazepine treatment and the effective dosages might be much lower than it used to treat epilepsy." (PMID 32246320, 2020). "Consistent with our result, this supports the hypothesis that differences in the epilepsy phenotypes in the patients with PRRT2 mutations depend on the types of PRRT2 mutations." (PMID 32509037, 2020). "Overall, status epilepticus seems a rare feature of PRRT2-associated epilepsy." (PMID 33126500, 2020). "PRRT2 mutation‐related epilepsy has incomplete penetration rate and phenotypic heterogeneity." (PMID 32237035, 2020). "Our report expands the mutation and clinical spectrum of PRRT2‐related epilepsy." (PMID 32237035, 2020). "Mutation of PRRT2 leads to an incompletely penetrant dominant form of epilepsy." (PMID 26893370, 2016). "We hypothesized that the PRRT2 mutation in the proband may only increase the risk of epilepsy, while another undiscovered mutated gene may instead contribute to the severe phenotype." (PMID 26544041, 2015). "In summary, we demonstrate that although pathogenic PRRT2 variants are most commonly associated with a SeLIE phenotype, atypical features may occur with seizures persisting later into childhood or the development of additional epilepsy phenotypes in others, such as IESS." (PMID 40401013, 2025). "However, additional epilepsy phenotypes may be observed with heterozygous PRRT2 variants." (PMID 40401013, 2025). "Genetically, MA overlaps with epilepsy-related loci (e.g., PRRT2), while MO is enriched in pain-modulatory genes (e.g., LRP1) and CGRP pathways (CALCA)." (PMID 40826382, 2025). "In this study, we report an additional cohort of PRRT2-related epilepsy/seizures and highlight commonalities to previous descriptions as well as atypical features of the condition." (PMID 40401013, 2025). "These CNVs contained or partially contained epilepsy-related genes, such as PRRT2 (16p11.2), ZBTB18 (1q43q44), and GABRB3 (15q11.2q13.1)." (PMID 39906551, 2024). "Using gene co-expression and interactome analysis, we show that PRRT2 is a major hub in the epilepsy subnetwork." (PMID 36808153, 2023). "In PRRT2‐related epilepsy, a prompt decision regarding anti‐seizure medication is often required because of clustered seizures at the initial presentation." (PMID 36775847, 2023). "It has recently been reported that VPA showed poor results on PRRT2-related epilepsy, and only three patients were treated with VPA." (PMID 37880614, 2023). "A few studies on LEV’s ineffectiveness have been reported in patients with SeLIE associated with PRRT2 mutations, and the mechanism of LEV’s inefficacy or exacerbation of PRRT2-related epilepsy is unclear." (PMID 37880614, 2023). "For example, EA and epilepsy associations include EA1 (KCNA1), EA2 (CACNA1A), EA5 (CACNB4), EA6 (SLC1A3), SCN2A, KCNA2, ATP1A3, SLC2A1, and PRRT2." (PMID 37008993, 2023). "Patients with PRRT2‐related epilepsy had characteristic seizure semiology at the initial presentation, including all afebrile, clustered (n = 23, 63.9%), short‐duration (n = 33, 91.7%), and bilateral tonic–clonic seizures (n = 26, 72.2%)." (PMID 36775847, 2023).
epilepsy (continued). "Our results delineated the clinical characteristics of PRRT2‐positive SeLIE, differentiating it from other genetic infantile epilepsies and discovered the effective anti‐seizure medications for initial clustered seizure control." (PMID 36775847, 2023). "This study delineates the clinical characteristics and response to anti‐seizure medications in patients with PRRT2‐positive SeLIE, distinguishing them from those of other early‐life epilepsy syndromes." (PMID 36775847, 2023). "Six atypical cases were included to expand our understanding of the clinical spectrum of PRRT2‐related epilepsy: three patients with neonatal‐onset seizures and three with unremitting seizures after 3 years of age." (PMID 36775847, 2023). "The data from the PRRT2 interactome suggested a close relationship between PRRT2, presynaptic function and biological pathways relevant to epilepsy." (PMID 36808153, 2023). "Using IAP-MS in the mouse neocortex, we showed that PRRT2 interacts with a broad range of proteins, enriched in presynaptic function and products of ID and epilepsy genes." (PMID 36808153, 2023). "PRRT2‐related epilepsy has normal neurodevelopmental milestones and spontaneous remission of seizures before two to 3 years of age, approximately." (PMID 36775847, 2023). "Thirty‐six patients (20 females and 16 males) diagnosed with PRRT2‐related epilepsy were included in this study." (PMID 36775847, 2023). "Other management changes included referrals to other specialties due to risk of nonneurological manifestations and weaning of an antiseizure medication after genetic diagnosis suggested a self-resolving epilepsy (eg, PRRT2)." (PMID 37471090, 2023). "Proline-rich transmembrane protein 2 (PRRT2) is the single causative gene for pleiotropic paroxysmal syndromes, including epilepsy, kinesigenic dyskinesia, episodic ataxia, and migraine." (PMID 36958475, 2023). "Our study findings can aid in identifying patients with PRRT2‐related epilepsy at an early stage of the disease and suggest a suitable first‐line anti‐seizure medication." (PMID 36775847, 2023). "The patient's group also included some patients with neonatal‐onset seizures and those with unremitting seizures, even after 3 years of age, to investigate the extended spectrum of PRRT2‐related epilepsy." (PMID 36775847, 2023). "PRRT2-related epilepsy is the most common monogenic epilepsy with an incidence of 1 per 9,970 live births." (PMID 38125836, 2023). "Epilepsy caused by the KCNQ2, KCNQ3, PRRT2, SCN2A and SCN8A gene are relatively benign with mild symptoms and consequences." (PMID 35571021, 2022). "PRRT2-related epilepsy provides a good example of repurposing drugs that had already been proved effective for a movement disorder caused by the same gene." (PMID 35250833, 2022). "In clinical practice, we identified a heterozygous nonsense mutant in the PRRT2 gene (c.649C>T; p.R217X) in a male patient exhibiting classic epilepsy and paroxysmal dyspraxia phenotypes, similar to patients carrying PRRT2 mutants reported previously." (PMID 34997978, 2022). "Transdermal nicotine treatment was successfully used in a CHRNA4-related case and carbamazepine in KCNQ2 and PRRT2 epilepsy." (PMID 33726816, 2021). "For genes associated with neonatal and infantile epilepsies, including KCNQ2, KCNT1, PRRT2, and SCN8A, we found that EMR usage was concentrated in the first year of life." (PMID 34031551, 2021). "It is also noteworthy that PRRT2 mutations were identified in both PKD patients and epilepsy patients." (PMID 32592228, 2020). "Mutations in 17 children were found by targeted sanger sequencing of PRRT2, while 23 patients were analyzed with an epilepsy gene panel (n = 21) or whole-exome sequencing (WES, n = 2)." (PMID 33126500, 2020).